RHO (rhodopsin)
Diseases named in the same sentence as RHO in open-access papers (continued):
Sharing a sentence is not in itself a finding about the gene and the disease.
autosomal dominant retinitis pigmentosa (continued). "Heterozygous variants in the RHO gene encoding for rhodopsin (RHO), a visual 348 amino acid G‐protein‐coupled receptor, are the leading cause of autosomal dominant retinitis pigmentosa (RP), which is a group of inherited retinal degenerative diseases due to loss of rod/cone photoreceptors." (PMID 40536197, 2025). "T17M rhodopsin mice, carrying a mutant human rhodopsin (RHO) gene, have become a valuable murine model for studying autosomal dominant retinitis pigmentosa (ADRP)." (PMID 27144303, 2016). "Here, we show that the synthetic transcriptional repressor (TR; ZF6-DB), designed to treat Rhodopsin-mediated autosomal dominant retinitis pigmentosa (RHO-adRP), does not perturb murine retinal development, while maintaining its ability to block Rho expression transcriptionally." (PMID 34071252, 2021).
retinal disease (25 papers, 2009 to 2025). "As RHO mutations are responsible for a large proportion of inherited retinal diseases, there has been great interest in developing genetic therapies for halting or reversing rhodopsin-mediated degeneration." (PMID 39556729, 2024). "A common inherited retinal disease is caused by mutations in RHO expressed in rod photoreceptors that provide vision in dim ambient light." (PMID 32724127, 2020). "Some features of retinal disease of patients with Class B RHO-adRP are modeled well in a naturally occurring dominant retinopathy due to a T4R mutation in the canine RHO gene." (PMID 32724127, 2020). "For example, mutations in rhodopsin are a leading cause of blindness, with over 150 rhodopsin mutations associated with human retinal disease." (PMID 29700553, 2018). "Some forms of inherited retinal disease show sectoral retinal pigmentary changes with a predilection for inferior and nasal involvement; this phenomenon is commonly associated with pathogenic RHO variants but has also been noted in connection with other genes." (PMID 39632990, 2025). "A subset of patients was screened for mutations in retinal disease genes, and mutations in the following genes were found: three cases with USH2A; three cases with EYS; one case each with USH3A (CLRN1), DHX38, RHO, RPGR, and RP9." (PMID 33037922, 2021). "Previous work had shown detectable but small structural changes to subcellular structures of photoreceptors occurring at transition zones (TZs) between retinal disease and health in Class B RHO-adRP patients." (PMID 32724127, 2020). "We demonstrate that variation in rhodopsin expression efficiently predicts candidate genes for eight uncloned retinal diseases, including WDR17 for the human RP29 locus." (PMID 19727342, 2009). "In summary, multiplexing of a biologically straightforward protein trafficking assay across a collection of every missense variant efficiently produced a large volume of structural and pharmacogenomic information about RHO, an important inherited retinal disease gene." (PMID 40093169, 2025). "Dark rearing that slows photoreceptor degeneration in several retinal disease models (e.g., those with dominant rhodopsin mutations or with loss of the visual arrestin) did not have any impact on visual responses of Rabgef1-/- mice." (PMID 33362196, 2020). "These techniques add new versatility to X. laevis as a research subject, and are likely to be highly useful for cell and developmental biologists, including those conducting research on rhodopsin function and rhodopsin gene regulation, and retinal disease mechanisms." (PMID 28761125, 2017). "The mechanisms regulating rhodopsin expression have been extensively studied for a number of years, both as a model of photoreceptor gene expression in general and because expression of rhodopsin has implications for retinal disease." (PMID 27977714, 2016). "Because the SAG gene product serves to turn off activated rhodopsin during the phototransduction cascade, it may be that the “toxic molecule” in SAG associated retinal disease is the activated but unquenched opsin apoprotein." (PMID 24019744, 2013). "Rhodopsin continues to serve as both a model system for GPCR biology and a critical therapeutic target for inherited retinal diseases, most notably adRP." (PMID 41009537, 2025). "Overall, the photoreceptor cells appeared intact on HE and rhodopsin immunostaining, indicating the potential utility of this model for RPE-originated retinal diseases." (PMID 38698112, 2024). "We propose that the analysis of functionally-relevant non-coding regions in rhodopsin, ABCA4 and other known retinopathy genes, as identified in this study, would greatly augment our understanding of Mendelian retinal diseases." (PMID 36207300, 2022).
retinal disease (continued). "The ciliary protein interactome appeared abnormal in all RGPRIP1 variant organoids and was sufficient to perturb the transport of rhodopsin and L/M-opsin to the OS of photoreceptors, a phenotype that has been described in RPGRIP1 null murine models and other retinal disease organoid models." (PMID 41270749, 2025). "Targeted region sequencing containing 156 retinal diseases-related genes of the proband (III:2) revealed a transversion in exon 5 (c.1015A > T) of RHO, which was not reported previously." (PMID 34635090, 2021). "The large number of inherited retinal disease genes (IRD), including the photopigment rhodopsin and the photoreceptor outer segment (OS) structural component peripherin 2 (PRPH2), has prompted interest in identifying common cellular mechanisms involved in degeneration." (PMID 33138244, 2020).
Blindness (18 papers, 2013 to 2025). Blindness is the condition of lacking visual perception defined as a profound reduction in visual perception. "Rhodopsin, a cilia-specific G-protein-coupled receptor (GPCR), is transported with high fidelity to the outer segment (OS) of vertebrate rod cells; disruption in rhodopsin trafficking results in photoreceptor apoptosis and RP-associated blindness." (PMID 41210874, 2025). "Legal blindness was reached at an earlier age in patients with RPGR mutations (median 45 years) than in patients with USH2A mutations (median 58 years) or RHO mutations (median 77 years)." (PMID 32571342, 2020). "Rhodopsin mislocalization is a common cause of photoreceptor degeneration in inherited blinding disorders." (PMID 32376599, 2020). "Mutations in rhodopsin can lead to misfolding of the protein within the ER and are known to cause the progressive blinding disease, RP." (PMID 31920544, 2019). "Astonishingly, the cvi of w1118 males towards intact females in daylight was also considerably lower than that of blind ninaB360d males (p<0.001), whose blindness is caused by a block in the synthesis of the retinal chromophore of rhodopsin." (PMID 24205022, 2013). "Their results further indicate that congenital blindness caused by constitutively active rhodopsin might be treatable with inverse agonist drugs that disrupt the rebinding of ATR to active rhodopsin." (PMID 37687205, 2023). "Finally, we showed that Nfe2l1 overexpression delayed visual loss in a preclinical model of human blindness caused by a misfolded protein called rhodopsin." (PMID 37450596, 2023). "Rhodopsin mutation is responsible for the apoptosis of rod and cone photoreceptors, triggering general disorganization and remodeling of the whole retina with the subsequent visual field and VA losses, ending in blindness in the final stage." (PMID 32784376, 2020). "Rhodopsin is involved in the transmission of the visual signal in the retina and its misfolding/mistrafficking, due to the absence of endogenous chromophore 11-cis-retinal or to structurally destabilising mutations, causes different severe inherited eye diseases, ultimately leading to blindness." (PMID 33114011, 2020).
breast carcinoma (18 papers, 2009 to 2025). "We believe that the observed changes in the morphology and impeded motility of the breast cancer cells after exposure to PCAIs are due to the disrupted F-actin organization, depleted levels of RHO GTPases, and vinculin punctate disruption." (PMID 38540084, 2024). "The combination of curcumin and rhodopsin synergistically inhibits breast cancer cell proliferation and invasion through upregulation of miR-34a." (PMID 39224778, 2024). "They demonstrated increased activity of GTP-bound RHOC and RHOA in tumors compared to natural tissues, and showed that RHO expression and RHO activation are two independent parameters in the different types of breast cancer." (PMID 35933373, 2022). "WNT11 was also shown to mediate WNT/PCP signaling via the RHO/ROCK pathway affecting the aggressive phenotype of breast cancer cells." (PMID 35668332, 2022). "WNT11 binds to the CRD of ROR2 and mediates WNT/PCP signaling via the RHO/ROCK pathway that confers an aggressive phenotype to breast cancer cells." (PMID 34911552, 2021). "In breast cancer cells, Gas6/Axl signaling also leads to rac activation and invasion through the scaffold protein Elmo and the RHO-GTPase activator DOCK1." (PMID 26356564, 2015). "Remarkably, our six-miRNA signature and genes related to the RHO-ROCK adhesion pathway were indeed prognostic for OS in breast cancer, after adjusting for age and stage." (PMID 25970788, 2015). "nEASE analysis also suggests that GIPC1 is involved in six major signal transduction networks in breast cancer: integrin-mediated, RHO protein, JAK-STAT, EGF, TGFβ and WNT." (PMID 21209904, 2010). "In fact, previous studies have indicated a role for lipophilic statins such as Simvastatin and Lovastatin as inhibitors of farnesyl transferase activity and RAS/RHO activity and to have the capacity to inhibit the growth of breast cancer cells in vitro." (PMID 19714244, 2009). "Alternatively, induction of RHO and PI3K signaling in metastatic breast cancer could be caused by additional genetic and epigenetic alterations, post-translational modifications, or external cues from the tumor microenvironment." (PMID 37463901, 2023). "The RHO GTPase–MVA pathway–YAP/TAZ axis has also been shown to be required for the proliferation and/or self-renewal of breast cancer and leukemia cells." (PMID 35565457, 2022). "Taken together, we show for the first time that ROR2 can trigger an autocrine, invasion-promoting signaling response via RHO/ROCK by inducing expression of its own ligand, WNT11, in human breast cancer." (PMID 34911552, 2021). "In the present study, we report that the expression of mevalonate pathway enzymes is mediated by the RHO guanosine nucleotide exchange factors VAV2 and VAV3 in a RAC1‐ and sterol regulatory element‐binding factor (SREBF)‐dependent manner in breast cancer cells." (PMID 39119789, 2025). "RHO GDI2 has been shown to be a metastasis suppressor in bladder and breast cancers." (PMID 25751262, 2015).
night blindness (17 papers, 2010 to 2025). Inability to see clearly in dim light. "In one with retinal dystrophy and night blindness, where the causal variant was RHO Gly90Asp, the gene was 100% homoplasmic." (PMID 39858655, 2025). "For instance, the A292E mutation in human rhodopsin has been shown to result in constitutively active apoproteins, leading to congenital night blindness." (PMID 40889130, 2025). "Patients with LCA who harbor RPE65 mutations exhibit a deficiency in photoreceptor rhodopsin, leading to severe night blindness and visual impairment following birth." (PMID 38264046, 2023). "This impairs chromophore, 11-cis-retinal, and slows rhodopsin (RHO) regeneration which can cause night blindness." (PMID 35162940, 2022). "The importance of correct rhodopsin levels in PRs is exemplified by the condition night blindness, where dietary deficiency of vitamin A, the chromophore that binds rhodopsin, results in an inability to see in low light." (PMID 28507272, 2017). "Night blindness-associated mutations often cause RHO to constitutively activate the phototransduction cascade at a low level." (PMID 27812022, 2016). "In the rods, for example, G90D, T94I, A292E and A295V rhodopsin mutations result in a form of congenital night blindness (nyctalopia) despite rod photoreceptors being maintained nearly intact across the human life span." (PMID 25650393, 2015). "By comparison, many rhodopsin mutations (such as T17M, P23H) are associated with night-blindness from a degenerative progressive RP phenotype." (PMID 25650393, 2015). "Retinol deficiency causes nyctalopia due to deficient rhodopsin formation." (PMID 41008379, 2025). "First affecting vision, the depletion compromises rhodopsin production, resulting in night blindness." (PMID 40970261, 2025). "The gene RHO, involved in photoreception, is central in both HA and t(HA, MA), and is also related to eye diseases, including night blindness." (PMID 29161290, 2017). "Nyctalopia has also been reported with isotretinion and is thought to develop due to hypovitaminosis A, which results in a reduction in rhodopsin for the photoreceptors." (PMID 21738614, 2011). "This SNP alters the visual pigments retinal binding site of the protein coded by the RHO gene, resulting in night blindness." (PMID 20886114, 2010). "Since data available from family members other than the index showed exclusively night blindness without any signs that point towards a progressive retinal degenerative process, we speculate that the RHO mutation p.E113K might cause Riggs-type CSNB also in other patients." (PMID 27812022, 2016).
Retinal dystrophy (16 papers, 2013 to 2025). Retinal dystrophy is an abnormality of the retina associated with a hereditary process. "In this study, the experience of the Laboratory of Genomic Medicine UILDM at Fondazione Santa Lucia IRCCS in the diagnosis of inherited retinal dystrophies was exploited to evaluate the distribution of RHO variants in the Italian patients." (PMID 39336749, 2024). "Several types of pharmacological compounds have been experimentally and clinically tested to treat retinal dystrophies caused by rhodopsin mutations." (PMID 37077319, 2023). "While the mechanisms underlying rhodopsin-related retinal dystrophy have been systemically reviewed previously, here, we focus more on well-studies mechanisms that have been utilized for the development of potential therapeutic approaches." (PMID 37077319, 2023). "Retinal dystrophy associated with rhodopsin mutations is an inherited disease with a pathogenesis that largely stems from cellular autophagy induced by abnormal retinoid binding to mutant proteins leading to cytotoxicity." (PMID 37077319, 2023). "Genetic etiologies of retinal dystrophy causing both autosomal dominant and recessive disease have been described in the literature and include RHO, RP1, BEST1, GUCY2D, RAX2, and RPE65." (PMID 31856884, 2019). "Defects in Rhodopsin trafficking in humans are a major cause of retinal dystrophy, and work in flies strongly suggests that it is, at least in part, defects in Rhodopsin trafficking that cause light induced degeneration in crb mutant photoreceptors." (PMID 29651238, 2018). "Therefore, it appears that deficiency of all the proteins reported to be located at the bulge region cause retinal dystrophy and most of them are associated with mislocalisation of rhodopsin." (PMID 39934925, 2025). "Given that RHO mutations have been traditionally associated with retinal dystrophies, this observation may point toward a broader phenotypic spectrum or gene–gene/environment interaction contributing to myopia pathogenesis." (PMID 40837568, 2025). "For instance, continuous delivery of CNTF to the retina of rhodopsin-deficient mice conferred lifelong protection to a significant fraction of cone photoreceptors and prevented the loss of cones over a time period of up to ~ 3 years in patients with hereditary retinal dystrophies." (PMID 32932933, 2020). "Previous investigations have indicated increased apoptosis in the ONL of canine and iPSC-RO models of retinal dystrophies with rhodopsin defects and mislocalisation." (PMID 35330501, 2022). "This domain-dependent effect on phenotype has been described in a number of other retinal dystrophies, including those associated with RP1 and RHO, which exhibit similar domain-dependent effects on protein function, disease presentation, and patterns of inheritance." (PMID 31856884, 2019). "While two week old KO animals were ostensibly normal, three week old KO animals exhibited significant retinal dystrophy as they were almost completely depleted of RHODOPSIN and displayed much lower amounts of two structural OS proteins and two phototransduction proteins." (PMID 30254279, 2018). "To date, proof‐of‐concept of AONs has been shown in both cell‐based models and animal models for four retinal dystrophy genes: CEP290, CHM (Garanto, van der Velde‐Visser, Cremers, & Collin, 2018), RHO, and USH2A, and represents a promising therapy for retinal dystrophies." (PMID 30950243, 2019).
congenital stationary night blindness (12 papers, 2013 to 2024). "There are currently over 100 known mutations in the rhodopsin G protein-coupled receptor that cause a spectrum of visual retinopathies including autosomal dominant retinitis pigmentosa (adRP) and congenital stationary night blindness (CSNB)." (PMID 35850308, 2022). "A mutation in the gene for rhodopsin corresponding to a substitution of glycine 90 by aspartic acid (G90D) is found in one form of congenital night blindness, and the corresponding amino acid replacement was introduced into rhodopsin for in vitro molecular studies." (PMID 36909961, 2022). "This symptomatology is also characteristic of vitamin A deficiency, congenital stationary night blindness (CSNB), Oguchi disease or RP, diseases that are directly linked to the malfunction of Arrestin-1 and GRK1, and Rhodopsin and Transducin-α." (PMID 36766830, 2023). "Six genes encoding major components of the phototransduction cascade (RHO, GNAT1, PDE6B, GRK1, and SAG) and the regeneration of the visual pigment (RDH5) are described in congenital stationary night blindness (CSNB) patients." (PMID 24760071, 2014).